CCDC159 (coiled-coil domain containing 159)
Description:
Functions during spermatid development; may participate in the centrosome reduction procedure of spermatids and is required for the formation of the connecting piece/sperm head-tail coupling apparatus (HTCA) and the correct and tight attachment of the flagellum to the nuclear envelope.
Tractability: PROTAC: ubiquitination databases record sites on it.
Gene: Protein-coding gene on chromosome 19 (11,344,684 to 11,354,944, forward strand). Ensembl gene ENSG00000183401.
Subcellular location (Human Protein Atlas): Nuclear bodies; Nucleoplasm; Cytosol
Gene Ontology:
Biological process: spermatid development
Cellular component: sperm head-tail coupling apparatus
Genetic constraint (gnomAD): Loss-of-function variants: 38 observed, 44.86 expected, observed/expected ratio (o/e) 0.85, 90% interval 0.65 to 1.11. The upper end of that interval is the gene's LOEUF score, 1.11, which puts it in group 4 of 6, group 1 being the genes least tolerant of losing a copy. Missense variants: 356 observed, 337.88 expected, observed/expected ratio (o/e) 1.05, 90% interval 0.96 to 1.15. Synonymous variants: 146 observed, 119.2 expected, observed/expected ratio (o/e) 1.22, 90% interval 1.07 to 1.4.
Homologues: Orthologues: chimpanzee CCDC159 (98% identical), macaque CCDC159 (93% identical), rabbit CCDC159 (83% identical), pig CCDC159 (80% identical), mouse Ccdc159 (74% identical), rat Ccdc159 (74% identical).